CP (ceruloplasmin)
Diseases named in the same sentence as CP in open-access papers (continued):
Sharing a sentence is not in itself a finding about the gene and the disease.
infection (continued). "It showed that CP-IDL could inhibit infection of all those different types of HIV-1 pseudovirus with IC50 values between 1.21 nM and 74.49 nM, which were much more potent than CP peptide (3.1 fold to 52 fold) or T20 (2.8 fold to 21.6 fold)." (PMID 27666394, 2016). "Calprotectin (CP, S100A8/S100A9 oligomer, MRP-8/14 oligomer, calgranulins A and B) is a protein component of the innate immune system that contributes to the metal-withholding response by sequestering bioavailable transition metal ions at sites of infection." (PMID 26925211, 2016). "Finally, the silent and severe infection groups had higher levels of IL-17+CD4+ and IL-17+CD8+ cells at the CP relative to their levels at baseline and relative to those in the control and minor infection groups." (PMID 24646014, 2014). "Comparisons between the two actively infected groups (CP Ag+ compared to INF) and those without active infection (CP Ag− compared to EN) were used preliminarily to identify markers of pathogenesis." (PMID 22685406, 2012). "SIV CP-MAC is of interest because its Env has been reported to exhibit CD4-independent utilization of rhesus CCR5 on Env-pseudotyped reporter particles, in contrast to viruses such as SIVmac239 where infection is CD4-dependent." (PMID 21203482, 2010). "The overexpression test displayed that viral CP mRNA and protein levels were lower in the NbCRVP overexpression treatment group than in the control group under infection of TMV, PVY, and CMV, respectively, further verifying that NbCRVP can inhibit the infection of RNA viruses in plants." (PMID 38191434, 2024). "However, MtsABC is dispensable for GAS pathogenesis in CP−/− mice, highlighting the significance of Mn in host–GAS interactions in vivo and the contribution of MtsABC to overcome the host-imposed Mn limitation during infection." (PMID 38869295, 2024). "In addition to the CP and MP genes, ORF2b of PLRV could also confer resistance to PLRV via a PTGS mechanism, and grafting infection experiments showed that resistant transgenic plants could be obtained in this way." (PMID 35627117, 2022). "Our studies, however, demonstrate that CP infusion did not abate a nascent infection." (PMID 33483492, 2021). "In vitro CP antiviral activity evaluated against Influenza A virus (PR8), Vesicular Stomatitis Virus (VSV), Newcastle Disease Virus (NDV), Herpes Simplex Virus (HSV), Coxsackie Virus (H3-GFP) and Enterovirus-71 (EV-71) infection on immune (RAW264.7) and epithelial (HEK293T/HeLa) cells." (PMID 27484768, 2016). "The infection induced degranulation was inhibited by pre-injection with BP (16.3%), whereas injection with CP failed to block it and 6.1% of the R1 population showed evidence of degranulation which is comparable with that observed in the infected control group." (PMID 24098508, 2013). "Third, by comparing TCD8+ responses to 46-SIINFEKL-16, a form of OVA that is not cross-presented and 61-SIINFEKL-121, a form of OVA that is cross-presented, we showed that CP is not essential for full-fledged TCD8+ responses to VACV independent of the route or dose of infection." (PMID 20169189, 2010). "Therefore, whether an outbreak or infection is due to a carbapenemase-producing CRO (CP-CRO) or a non-carbapenemase-producing CRO (non-CP-CRO) has implications for prevention and control." (PMID 38698944, 2024). "The incidence of BSIs by MRSA and carbapenem-resistant P. aeruginosa remained stable during the study period (especially after 2018); this probably rules out the possibility of a breach in infection control protocols, which could explain the change in CP-Kp BSIs epidemiology." (PMID 36290072, 2022). "Western blot experiments performed at 10 dpi with anti-PVX CP antibody and anti-Myc antibody confirmed that C4 could remarkably increase PVX accumulation, further implying that C4 may be a pathogenic determinant independent of ToLCGdV infection." (PMID 32431688, 2020).
infection (continued). "Similarly, the CP8unalikevirus phage CP_F1 showed decreased infection efficiency on non-motile cells, as infection of flaA and flaAB mutant strains yielded reduced efficiency of plating (EOP) values (flaA 0.08 ± 0.04, n = 3; flaAB 0.12 ± 0.03, n = 3) and highly opaque plaques." (PMID 27965643, 2016). "In addition, ceruloplasmin was found to be similar in aGvHD patients with or without infection." (PMID 23505556, 2013). "Because ceruloplasmin is an acute-phase reactant that may be involved in inflammatory processes such as infection, 31 patients without infections at fixed time points were chosen for the evaluation of the impact of only aGvHD on the kinetics of ceruloplasmin following allo-HSCT." (PMID 23505556, 2013). "However, while ceruloplasmin is an acute phase protein where plasma levels are increased in the serum during infection and inflammation, a direct link between ceruloplasmin and the provision of Cu to innate immune cells during infection has not been made." (PMID 23028306, 2012). "Hospital A sent a contact precaution recommendation based on CP-CRPA detection, but it was not directed to hospital B’s infection preventionist." (PMID 37535466, 2023). "A significant interaction effect existed for SP × EC on some antioxidant biomarkers, indicated by modulating the negative impact of EC infection on GSH and CP levels in the SP-supplemented birds." (PMID 36766252, 2023). "The accumulations of SCMV RNA and CP proteins were not changed after SCMV infection, while they were significantly reduced after S + M infection both in ZmNQO1- and ZmTAT-silenced plants through RT–qPCR and Western blot assays." (PMID 37175719, 2023). "While severe mosaic, mottled and crinkled leaves were observed in the infected leaves of wild-type and St-CP#7 transgenic plants, almost no disease symptoms were observed in the Cas13d/PTG transgenic plants in the mixed infection of PVY/PVX or PVS/PVY." (PMID 37591976, 2023). "In accordance with the other infection parameters, viral load in upper non-inoculated leaves, inferred from UCBSV CP immunodetection, was slightly higher in plants infected with the wild-type virus." (PMID 35180277, 2022). "Our data showed that OR of CP-CRE was far less than that of KPC-CRE (3.993 vs. 13.028), suggesting that the correlation between CP-CRE colonization and subsequent infection was not as strong as KPC-CRE." (PMID 34215214, 2021). "Taken together, synergistic infection of BrYV and PEMV 2 increased the accumulations of both BrYV RNA and CP, while did not have much effect on the accumulation of PEMV 2 RNA." (PMID 28345652, 2017). "Markers of pathogenesis were delineated based on comparisons between the two actively infected groups (CP Ag+ compared to INF) and those without active infection (CP Ag− compared to EN)." (PMID 22679524, 2012). "On the other hand, consistent with our results with the transfection/infection system, infection of A9 cells with recombinant VACV 61-SIINFEKL-121 but not with VACV 46-SIINFEKL-16 resulted in CP in vitro and CP to OT-I cells in vivo." (PMID 20169189, 2010). "However, Mn acquisition by MtsABC is dispensable for GAS virulence in mice lacking CP, emphasizing the direct competition for Mn between host-derived CP and GAS Mn importer MtsABC during infection." (PMID 38869295, 2024). "When mutated and wild-type versions of UCBSV-2xMYC were inoculated in N. benthamiana (n = 2 per virus), all of them produced indistinguishable infections, with comparable symptoms and virus accumulation in upper non-inoculated leaves as observed by immunodetection of UCBSV CP." (PMID 35180277, 2022).
tumor (155 papers, 1976 to 2026). "Among iron-related markers, ceruloplasmin and the ceruloplasmin/transferrin ratio were significantly associated with tumor stage (pT), tumor size, metastasis, and tumor grade, particularly in males." (PMID 40507970, 2025). "Our final objective was to determine the association between CP levels and tumor responses to chemotherapy." (PMID 39337685, 2024). "CP is a plasma protein for copper binding and is associated with various immune pathways and inflammatory responses related to the tumor microenvironment." (PMID 38951817, 2024). "By identifying 20 tumor-specific markers through a multi-omics tiered approach, we reveal an association between higher ceruloplasmin (CP) expression and reduced survival." (PMID 36973268, 2023). "High tumor-cell expression levels of CP and PCSK6 (from snRNA-seq) are associated with higher tumor grades (FDR < 1e−10; G3 and G4 vs. G1 and G2)." (PMID 36973268, 2023). "Researchers found that urinary ceruloplasmin (CP) levels were associated with tumour grade and pT stage in patients with NMIBC." (PMID 35955727, 2022). "To clarify the molecular mechanism of ZEB1 and CP, we divided the 471 tumor patients in TCGA into high- and low-risk groups." (PMID 35232428, 2022). "Recent evidence suggests that ceruloplasmin is also associated with tumor development and progression." (PMID 36147484, 2022). "Pathological detection of tumor tissues confirmed that the anti-cancer activities of CP were tightly associated with downregulated expressions of β-catenin, Cav-1, and Vimentin, and upregulation in the expression of E-cadherin." (PMID 34168559, 2021). "Ceruloplasmin expression was significantly associated with the infiltration of immune cells into tumor sites by analyzing the TIMER and CIBERSORT." (PMID 34413268, 2021). "Immunohistochemical staining of tumor samples for candidate genes associated with ceruloplasmin was weakly positive in 16 samples (20.3%), and strongly positive in 4 (5.1%)." (PMID 28423673, 2017). "In this context, our finding of reduced % transferrin saturation and elevated ceruloplasmin/transferrin ratios in CRC patients may reflect a tumor-associated shift aimed at limiting ferroptotic vulnerability." (PMID 40507970, 2025). "Furthermore, five targets associated with CP‐related features in the tumour and/or stroma regions were selected for verification by IHC on additional samples." (PMID 40697100, 2025). "Anomalous CP expression is linked with tumor development and progression." (PMID 38385087, 2024). "Down-regulation of matrisome-associated and inflammatory response genes associated with CP knockdown supported our hypothesis that CP may have a role in mediating tumor-stroma interactions." (PMID 36973268, 2023). "CP expression in BCa tissues was positively associated with tumour growth and progression." (PMID 35955727, 2022). "Furthermore, we retrieved the corresponding DEGs of HBV-associated HCC from GSE44074 microarray of 17 HBV-associated HCC patients and 71 individuals with non-tumor liver specimens to reveal how the active ingredients of CP act on the HBV-associated HCC." (PMID 34168559, 2021). "These proteins (haptoglobin, ceruloplasmin, and hemopexin) are components of serum, suggesting that the large number of serum proteins in both the Pap test fluid and swab underlies the similarity of these samples relative to the tumor sample." (PMID 33413078, 2021). "Elevated glycoconjugates could be the result of an inflammatory reaction associated with neoplasia, because serum ceruloplasmin which is an acute phase reactant, is also increased in those patients." (PMID 28423673, 2017). "First, previous studies have only analysed virological factors or oncogenes associated with HCC progression, whereas our study showed that the concomitant expression of AKT1 and HBV CP mutations corresponding to the CP mutations that are clinically associated with HCC promote tumour progression." (PMID 27779207, 2016).
tumor (continued). "Accordingly, the levels of E2F1 were significantly increased in TACO expressing HCC tissue, suggesting that HBV CP mutations may induce hepatocarcinogenesis and tumour progression via similar mechanisms." (PMID 27779207, 2016). "The change in serum concentration of ceruloplasmin, along with many other acute phase proteins identified among the differentially expressed proteins, implicated the presence of immune and inflammatory responses caused the tumor." (PMID 23251472, 2012). "Two of the genes that might be associated with the poor ability of shHIF cells to grow as tumor spheres are Jmjd1 and Ceruloplasmin." (PMID 20515450, 2010). "Downregulation of Jmjd1 and Ceruloplasmin, genes associated with stem cells, might be correlated with the poor ability of shHIF cells to grow as tumor spheres." (PMID 20515450, 2010). "Thus, the change in serum concentration of ceruloplasmin may indicate that it is an acute phase protein secreted in response to the oxidative stress in inflammation associated with the tumor and/or that it is secondary to the deficiency of total body copper." (PMID 23251472, 2012). "Therefore, the high ceruloplasmin level in ascites in our study may be caused by relatively advanced tumor metastasis associated with worse prognosis." (PMID 23251472, 2012). "The expression of ceruloplasmin may be associated with tumor progression." (PMID 23251472, 2012). "Specific sampling revealed stroma‐driven tumour heterogeneity, identifying 642 tumour‐specific and 180 stroma‐specific proteins, with 505 CP‐responsive therapeutic targets." (PMID 40697100, 2025). "In the tumour regions, a total of 136 and 42 DEPs‐cp with upregulated abundance were marked in the CP‐i and CP‐s samples, respectively, whereas in the stroma regions, 61 and 266 DEPs‐cp were noted, respectively." (PMID 40697100, 2025). "Consistent with previously research, our study also identified upregulation of genes (CP, HP and CYBA) associated with oxidative stress in moderately differentiated tumours." (PMID 40847563, 2025). "In healthy male mucosa, positive correlations between the ceruloplasmin/transferrin ratio and EMT markers suggest a coordinated regulation, while their loss in tumor tissue implies a disruption during CRC progression." (PMID 40507970, 2025). "Taken together, the TS distribution was very different from that of CS in CP‐i or CP‐s samples, and the generally higher CS values in the tumour and stroma in CP‐s samples imply some drug‐sensitive proteins being upregulated in these samples." (PMID 40697100, 2025). "Each spot on the HGSC FFPE samples had its own CS; therefore, the CS distributions of either tumour‐CS or stroma‐CS were profiled in the CP‐i and CP‐s samples." (PMID 40697100, 2025). "While IGFBP2 and CP displayed more expression in the cellular tumor zone toward the tumor center, LOX was expressed in the vascular regions at the periphery." (PMID 38339384, 2024). "In summary, we found that LINC02936, the TF SIX1, and its target gene CP are highly expressed and related to poorer outcomes in patients with EC, and act as an oncogenic role in regulating ferroptosis and tumor progression." (PMID 38385087, 2024). "The SerpinA3, PON1, and CP expression also remained unchanged in both the cardiac tissues and tumor in this model." (PMID 38279150, 2024). "These bacteria have the capacity to enhance the anti-tumor effect of CP by modulating the CP-mediated aggregation of Th1 and Th17 cells." (PMID 39021626, 2024). "We developed a peptide CP specificfor the tumor stem cell marker CD133 (KD ≈ 7 × 10–9 M) and prepared CP-IRTbased on a click-chemical reaction linking it to a near-infrared organicfluorophore." (PMID 39473775, 2024). "Once taken up by tumor cells, the mRNA is translated into ceruloplasmin protein, which supports iron export with lower rated of lipid peroxidation and ferroptosis." (PMID 39372215, 2024).
tumor (continued). "FeS2@CP NPs-based CDT efficaciously eradicated the tumor cells by initiating dual-effect of killing of apoptosis and ferroptosis." (PMID 38561739, 2024). "To determine the carcinogenesis of CP in EC in vivo, we established a xenograft tumor and lung metastasis assay in nude mice." (PMID 38385087, 2024). "CD45+EPC were pulsed with control or specific peptides (CP or SP) from MC38-ova or B16 tumor-bearing mice and co-cultured with splenocytes pulsed with specific peptides." (PMID 38799424, 2024). "This work presents a hybrid nanozyme composed of PEGylated Fe‐MOF nanoparticles and cholesterol oxidase, termed Fe‐MOF/CP, designed to initiate combinatorial tumor ferroptosis immunotherapy." (PMID 39120559, 2024). "More importantly, the level of SIX1 was consistently high in tumor tissue, > 60 years old, G3, dead group, and poor survival, which was consistent with CP in the TCGA-UCEC." (PMID 38385087, 2024). "Antibiotics targeting gram-positive bacteria significantly reduce the efficacy of CP, suggesting that gram-positive bacteria, such as Enterococcus and Lactobacillus, are key in modulating the anti-tumor efficacy of CP against hematological tumors." (PMID 39021626, 2024). "Due to the highest fold change between these groups, CP caught our particular attention, and further analysis indicated consistent high expression of CP in tumor tissues, > 60 years old, G3, and the dead group." (PMID 38385087, 2024). "In summary, these findings indicated that CP promoted tumor progression by inhibiting ferroptosis in EC." (PMID 38385087, 2024). "Apparently, tumor-associated macrophages protect tumor cells from RSL3-mediated ferroptosis because these macrophages release extracellular vesicles containing ceruloplasmin mRNA." (PMID 39372215, 2024). "We discover transcription factors regulating CP and glycolytic genes, which are differentially accessible and expressed between tumor cells and normal proximal tubule cells." (PMID 36973268, 2023). "We also demonstrated that targeting ATF5 using a cell-penetrating dominant-negative ATF5 peptide inhibitor (CP-d/n-ATF5) increased the anoikis sensitivity of tumor cells and inhibited metastasis." (PMID 38014922, 2023). "Consistent with the in vitro results, CP-FaP2 and CP-FaP3 suppressed xenograft tumor growth and decreased the expression of Ki67 and Wnt/β-catenin target genes in inoculated tumor tissues compared with that of the control peptides." (PMID 36797256, 2023). "CP knockdown, combined with spatial transcriptomics, suggests a role for CP in regulating hyalinized stroma and tumor-stroma interactions in ccRCC." (PMID 36973268, 2023). "Tumor 293 displayed enriched CP expression in an area showing a relative sparsity of tumor cells embedded in an abundant background of hyalinized stroma (location A) compared to the rest of the tumor (location B)." (PMID 36973268, 2023). "Despite being a ccRCC tumor marker, we know little about the molecular pathways and genes regulated by CP in ccRCC." (PMID 36973268, 2023). "High expression CP in tumor cells transfers electrons to oxygen and oxidizes Fe2+ to Fe3+ via regulating copper, thus reducing intracellular Fe2+ and inhibiting ferroptosis." (PMID 37637428, 2023). "Tumor 282 also showed higher CP expression in an area showing a higher hyalinization-to-cell ratio (location C) than in the rest of the cancer (location D), indicating partial regressive changes." (PMID 36973268, 2023). "Pan-cancer analysis suggested significant differences in CP expression between a variety of tumor tissues and paraneoplastic tissues." (PMID 37637428, 2023). "Mito-CP caused cytotoxicity mainly by inhibiting the mitochondrial activity critical to maintain bioenergetic and REDOX equilibrium, however the mitochondria-specific delivery of the CP fragment of Mito-CP is essential for tumor inhibition." (PMID 37954849, 2023).